RHEBL1 (RHEB like 1)
Description:
Binds GTP and exhibits intrinsic GTPase activity (By similarity). May activate NF-kappa-B-mediated gene transcription. Promotes signal transduction through MTOR, activates RPS6KB1, and is a downstream target of the small GTPase-activating proteins TSC1 and TSC2.
Synonyms: RhebL1c; MGC34869; FLJ25797; RHEB2
Tractability: Small molecule: a structure with a bound ligand is known; it has a binding pocket of medium quality. Antibody: its Gene Ontology location is reachable by antibodies, with medium confidence. PROTAC: ubiquitination databases record sites on it.
Gene: Protein-coding gene on chromosome 12 (49,064,676 to 49,070,039, reverse strand). Ensembl gene ENSG00000167550.
Subcellular location: Endomembrane system; Cytoplasm
Subcellular location (Human Protein Atlas): Centrosome; Nucleoli; Nucleoplasm
Gene Ontology:
Molecular function: GTP binding; protein binding; GTPase activity; protein serine/threonine kinase activator activity
Biological process: intracellular signal transduction; TOR signaling; positive regulation of TORC1 signaling; small GTPase-mediated signal transduction; signal transduction
Cellular component: cytoplasm; plasma membrane; endomembrane system; membrane
Genetic constraint (gnomAD): Loss-of-function variants: 23 observed, 29.84 expected, observed/expected ratio (o/e) 0.77, 90% interval 0.55 to 1.09. The upper end of that interval is the gene's LOEUF score, 1.09, which puts it in group 4 of 6, group 1 being the genes least tolerant of losing a copy. Missense variants: 185 observed, 237.72 expected, observed/expected ratio (o/e) 0.78, 90% interval 0.69 to 0.88. Synonymous variants: 85 observed, 85.96 expected, observed/expected ratio (o/e) 0.99, 90% interval 0.83 to 1.18.
Homologues: Orthologues: chimpanzee RHEBL1 (99% identical), macaque RHEBL1 (99% identical), pig RHEBL1 (96% identical), rabbit RHEBL1 (92% identical), mouse Rhebl1 (89% identical), guinea pig RHEBL1 (87% identical), rat Rhebl1 (87% identical), dog RHEBL1 (83% identical), tropical clawed frog rhebl1 (55% identical). Paralogues in human: RHEB (52% identical), RAP2B (38% identical), RAP1A (37% identical), RAP1B (37% identical), RAP2A (37% identical), DIRAS2 (35% identical), RAP2C (34% identical), RRAD (34% identical), RIT2 (34% identical), DIRAS1 (33% identical), HRAS (33% identical), KRAS (33% identical), and 23 more.
Diseases named in the same sentence as RHEBL1 in open-access papers:
RHEBL1 is named in the same sentence as 13 diseases in open-access papers, as found by Europe PMC text mining. Sharing a sentence is not in itself a finding about the gene and the disease. The quoted sentences say what the papers report.
breast carcinoma (2 papers, 2017 to 2022). "AKT1 might be a binding partner of RhebL1 in breast cancer cells." (PMID 28209923, 2017). "In breast cancer cells MCF7, scholars found that overexpression of RhebL1 increased the expression of mesenchymal markers and decreased the expression of E-cadherin in MCF7 and that downregulation of this gene significantly reduced the migration and invasion of MCF7 cells." (PMID 36386821, 2022).
lung carcinoma (2 papers, 2017 to 2022). "It has been found that RHEBL1 is involved in sphingosylphosphorylcholine-induced events in A549 lung cancer cells via binding to AKT1 leading to activation of it." (PMID 36386821, 2022). "Lung cancer patients were divided into two subgroups (RhebL1-high and RhebL1-low) based on their median expression level." (PMID 28209923, 2017). "The collective findings indicate that RhebL1 is involved in SPC-induced events in A549 lung cancer cells by activation of AKT1." (PMID 28209923, 2017). "We found that the overall survival was high in lung cancer patients having low expression level of RhebL1 (n = 1145, p = 0.00094)." (PMID 28209923, 2017). "Lung cancer patients were divided into two subgroups (‘RhebL1-high & AKT1-high’ and ‘RhebL1-low & AKT1-low’) on the basis of their median expression level." (PMID 28209923, 2017). "Gene silencing of RhebL1 inhibited SPC-induced phosphorylation of S431 in K8 in lung cancer cells including A549, H1299, H1703, and H838 lung cancer cells and reorganization of K8 in A549 lung cancer cells." (PMID 28209923, 2017). "In contrast, overexpression of RhebL1 induced phosphorylation of K8 in A549, H1299, H1703, and H838 lung cancer cells and reorganization of K8 in A549 cells, even without SPC treatment." (PMID 28209923, 2017). "The collective results indicate that RhebL1 is involved in sphingosylphosphorylcholine-induced events in A549 lung cancer cells via binding to AKT1 leading to activation of it." (PMID 28209923, 2017). "In this report, we describe SPC induction of RhebL1 expression in lung cancer cells." (PMID 28209923, 2017). "The induction of RhebL1 expression was also observed in H1703 and H838 lung cancer cells." (PMID 28209923, 2017). "We found that RhebL1 was increased in A549 or other lung cancer cells with SPC treatment." (PMID 28209923, 2017). "To investigate the involvement of RhebL1 in SPC-induced events including K8 phosphorylation, reorganization, migration, and invasion, we examined the effects of gene silencing and overexpression of RhebL1 on the SPC-induced events in A549 lung cancer cells." (PMID 28209923, 2017).
leukemia (1 paper, 2013). A malignant (clonal) hematologic disorder, involving hematopoietic stem cells and characterized by the presence of primitive or atypical myeloid or lymphoid cells in the bone marrow and the blood. "Previous studies reported that RHEBL1 could function as an activator of NF-kB and mTOR signaling, both of which are frequently altered in many solid tumors, as well as in leukemias and lymphomas." (PMID 24127550, 2013).
malignant mesothelioma (1 paper, 2022). A malignant neoplasm of the pleura or peritoneum, arising from mesothelial cells. "Several studies also found that high expression of exogenous RHEBL1 promoted the growth of malignant mesothelioma cells and probed that RHEB-mTORC1 signaling has a pro-carcinogenic effect." (PMID 36386821, 2022).
melanoma (1 paper, 2016). A malignant, usually aggressive tumor composed of atypical, neoplastic melanocytes. "The only other member of the subfamily (RHEBL1) shares a Y35H mutation in the same hotspot in one melanoma case in our dataset." (PMID 26860319, 2016).
non-small cell lung carcinoma (1 paper, 2022). A group of at least three distinct histological types of lung cancer, including non-small cell squamous cell carcinoma, adenocarcinoma, and large cell carcinoma. "In conclusion, low expression of RHEBL1 or high expression of RNPC3 was significantly associated with good prognosis in patients with non-small cell lung cancer." (PMID 36386821, 2022). "Overall, Protodioscin and Polyphyllin VI significantly promoted either low expression of RHEBL1 or high expression of RNPC3, causing patients with non-small cell lung cancer to exhibit a good prognosis." (PMID 36386821, 2022). "In conclusion, the expression of RHEBL1 and RNPC3 significantly correlated with immune cells infiltrated by tumors in patients with non-small cell lung cancer." (PMID 36386821, 2022). "Further testing revealed that low expression of RHEBL1 and high expression of RNPC3 in non-small cell lung cancer significantly improved the prognosis and prolonged life expectancy of cancer patients." (PMID 36386821, 2022). "In conclusion, our findings strongly suggest that RHEBL1 and RNPC3 are potential targets for Polyphyllin VI and Protodioscin in the treatment of non-small cell lung cancer, and may also be candidate diagnostic genes for non-small cell lung cancer-related prognosis." (PMID 36386821, 2022). "The intersection of the two was taken to screen five non-small cell lung cancer signature genes from the training sets GSE151103 and GSE33532: DOCK6, GPC2, RHEBL1, RNPC3, and PIWIL2." (PMID 36386821, 2022). "This suggests a high probability of diagnosing non-small cell lung cancer with RNPC3 and RHEBL1." (PMID 36386821, 2022). "The results of bioinformatics analysis, molecular docking, flow cytometry and quantitative PCR suggest that RHEBL1 and RNPC3 may be potential targets for Polyphyllin VI and Protodioscin in the treatment of non-small cell lung cancer." (PMID 36386821, 2022).
Obesity (1 paper, 2022). Accumulation of substantial excess body fat. "The colocalization analysis implicates genes involved in body mass index (BMI)/obesity and neuroticism (ARPP21, RP11-62H7.2, MFHAS1, RHEBL1)." (PMID 36297114, 2022).
schizophrenia (1 paper, 2020). A major psychotic disorder characterized by abnormalities in the perception or expression of reality. "The eQTLs identified here also provide insights into CNS traits and disorders, with co-localization in 13 of 108 GWAS loci for schizophrenia and 52 of 1,271 GWAS loci for educational attainment, including the lncRNA LOC101926933 and the protein-coding gene RHEBL1." (PMID 32268104, 2020).
vitiligo (1 paper, 2025). Generalized well circumscribed patches of leukoderma that are generally distributed over symmetric body locations and is due to autoimmune destruction of melanocytes. "Finally, we obtained ten matched genes (GP1BA, ANKS4B, CCDC87, CA8, HLA‐DOB, RHEBL1, NLRP7, GZMH, HERPUD1, and MAP2K1) as a vitiligo‐gene signature (VGS)." (PMID 40974370, 2025).
cancer (5 papers, 2013 to 2022). A tumor composed of atypical neoplastic, often pleomorphic cells that invade other tissues. "Interestingly, both DHH and RHEBL1 genes have been implicated in a variety of human diseases, including cancer." (PMID 24127550, 2013). "Results: 239 genes were identified for further survival analysis, 5 of which were overlapping genes across at least five cancer types, including RHEBL1, PDE4B, ANKRD55, EPHB2, and GIMAP7." (PMID 34262492, 2021).
RHEBL1 also shares sentences with these, for which no sentence is quoted: acute myeloid leukemia (1 paper); lymphoma (1); tumor (1).